CXCL2 (C-X-C motif chemokine ligand 2)
Diseases named in the same sentence as CXCL2 in open-access papers (continued):
Sharing a sentence is not in itself a finding about the gene and the disease.
infection (405 papers, 2007 to 2025). The state of being infected such as from the introduction of a foreign agent such as serum, vaccine, antigenic substance or organism. "We found that in comparison to the WT, infection with the ▵vapC12 strain enhanced the expression of genes that encode proteins implicated in neutrophil-mediated immunity in the host (Cxcl2, Trem1, S100A8/A9 and Ccl3)." (PMID 38515752, 2024). "In contrast, PMN depletion prior to infection in CXCL2-deficient mice resulted in lower viremia and increased survival." (PMID 34357089, 2021). "The induction of IL-8, IL-6, CXCL2 and IL-1α upon infection was significantly suppressed by overexpressing the mutated PUF60." (PMID 32538777, 2020). "Although the transcription of these chemokines in lungs of C57BL/6 or Gcnt1−/− mice was similar upon a low dose of infection, the expression of Cxcl2 was higher in Gcnt1−/− deficient mice than in C57BL/6 upon a high dose of infection." (PMID 32203062, 2020). "By contrast, infection with the ΔgliP mutant caused an increase in mRNA levels of CXCL2, CCL3, and CCL4, chemokines that are chemotactic for neutrophils." (PMID 30052103, 2018). "Indeed, genes within the IL-17 pathway including Cebpb, Tnf, IL-6, Cxcl1, Cxcl2, Cxcl3, Cxcl5, Cxcl10, and Ccl7 were shown to be up-regulated in both susceptible and resistant mice during infection." (PMID 29339782, 2018). "Between days 4 and 20, mice recovered from the infection in terms of weight changes and clinical symptoms, as well as in changes associated with inflammatory processes in the liver in terms of the Cu/Zn ratio and previous data on Cxcl2 and IFN-γ." (PMID 28691023, 2017). "Thus, hepatic CXCL2 deficiency will increase liver injury and the susceptibility to infections." (PMID 39619227, 2023). "Conversely, IL-27Rα KO neonates increase CXCR2 expression significantly in the spleen during infection but fail to upregulate CXCL2 transcripts." (PMID 40977737, 2025). "Limitations of this study include a detailed analysis of the source of CXCL2 in the spleen during infection." (PMID 40977737, 2025). "Nevertheless, genes related to anti-infection processes such as autophagy regulation (Plekhf1) or neutrophil recruitment (Cxcl2) were also induced." (PMID 41284621, 2025). "We further demonstrated that with regulated CXCL2 chemokine expression levels, IL-27Ra-deficient neonatal mice had more CXCR2+ mononuclear cells present at the site of infection." (PMID 40977737, 2025). "Infection also boosted the expression of the CXCL2, CCL2, CCL3, and CCL5 chemokines in female mice, while only CCL2 and CCL3 expression increased in males." (PMID 40143355, 2025). "Gene expression data from the spleens of WT and KO neonates confirmed that during infection, CXCL2 chemokine levels were highly elevated in the WT whereas KO had moderately elevated expression." (PMID 40977737, 2025). "Here we further explored the mechanistic insights of the CXCR2/CXCL2 signaling axis limiting the infection in WT and IL-27Rα KO neonatal mice using an n vivo model and ex vivo studies with primary cells." (PMID 40977737, 2025). "NMN treatment can reduce NF-κB signaling pathway activation in bone marrow-derived macrophages (BMDM) after hvKP infection, as well as the transcription of Il6, Il1b, Tnf, and Cxcl2." (PMID 40742124, 2025). "In contrast to the decreased levels of receptor, its ligand CXCL2 expression was highly upregulated in the WT pups during infection." (PMID 40977737, 2025). "One day after infection, the expression of Cxcl1, Cxcl2, Cxcl5, TNF-α, and IL-1β were 15 – 50-fold higher in lungs of Mki67WT mice exposed to hyperoxia when compared to Mki67WT mice exposed to room air." (PMID 40494897, 2025). "The results uncovered that during infection WT neonatal mice fail to increase expression of CXCR2 but upregulate the cognate ligand CXCL2 significantly." (PMID 40977737, 2025).
infection (continued). "Conversely, Pad2−/− mice showed a downregulation of M1‐related genes (Il1a, Il1b, Tnf, Cxcl2, Ccl4, Il12a, Cxcl1, Il6) compared to WT mice after PA infection." (PMID 40087815, 2025). "Analysis of macrophage‐related cytokines and chemokines found that Tnf, Il1b, Il1a, Ilrn, Il17ra, Cxcl1, Cxcl2, Ccrl2, Ccl3, Ccl4, and Ccl9 expression significantly increased over the course of infection." (PMID 41117166, 2025). "Macrophages express CXCR-2, which facilitates the release of chemokines such as CXCL-1 and CXCL-2 to recruit T cells to sites of inflammation or infection." (PMID 40585992, 2025). "Expression of the ligands Spp1, Cxcl2, and Cxcl3 were abundant in keratinocytes, fibroblasts, and M2-like macrophages during the infection." (PMID 38767331, 2024). "We found that the transcription levels of CXCL1 and CXCL2 were strongly increased in Trim26–/–mice at 1–5 days post-infection." (PMID 38166150, 2024). "Next, we evaluated G-CSF, CXCL1 and CXCL2 in circulation, as these are key cytokines regulating the mobilization of neutrophils out of the BM in response to injury or infection." (PMID 39509414, 2024). "For the gene expression analyses, the levels of interleukin (IL)-6 and C-X-C Motif Chemokine Ligand 2 (CXCL2) were significantly upregulated in the infection group (P < 0.001 and P < 0.01, respectively; n = 5; Tukey test) compared to the control." (PMID 38233485, 2024). "Similar to the findings in our transcriptional analysis, we found increased TNFα (P = 0.028) and CXCL1 (P = 0.0056) in the ECRG4 KO mouse infection, as well as a trend towards increased CXCL2, IL1β, and IL6." (PMID 39509414, 2024). "Compared to sham, RV-A1 increased mRNA expression of Cxcl2, Tnf-α and Muc5ac at 24 h post-infection in placebo-treated groups." (PMID 39538325, 2024). "The Cxcl2 plays a crucial role in inflammation by attracting and activating immune cells, particularly neutrophils, to sites of injury or infection." (PMID 38229193, 2024). "Significant decreases in CCL3, CCL4, and CXCL2 were observed in the galea of TNF KO mice at day 14 post-infection, corresponding to the timepoint and anatomical location where granulocyte recruitment was maximally reduced." (PMID 39044282, 2024). "Infection with Spn significantly increased expression of Cxcl1, Cxcl2 and lipocalin-2 (Lcn2), a marker of inflammation, in infant mice compared to adults." (PMID 38718049, 2024). "Examination of the single cell RNA sequencing dataset for markers associated with the wound-healing response revealed higher expression of several reparatory signaling genes during DPdh infection, including S100a9and Cxcl2 in myeloid cells." (PMID 38196634, 2023). "Several DEGs specific to cytokines Cxcl1, Cxcl2, Ccl3, and Il1b were upregulated in bone-marrow-derived macrophages at both 1 and 24 h post-infection with Bb validating the mRNA abundance observed in scRNA-Seq analysis of infected splenocytes." (PMID 38149246, 2023). "Cxcl1 and Cxcl5 production were induced in epithelial cells following chronic H. felis infection, while Cxcl2 and Cxcl3 production was induced in epithelial, myeloid, and T cell subsets following infection." (PMID 37744359, 2023). "Typical inflammatory chemokines, including Ccl4, Ccl3, Cxcl2, Cxcl3, and Cxcr2, induces immune cells to enter the site of infection during the immune response." (PMID 37580334, 2023). "Whereas the CXCL2 response mirrored that of IL-1, increasing steadily over the first 7d post-infection." (PMID 37724291, 2023). "Prior studies demonstrated that the activation of Cxcl1/Cxcl2 in murine macrophages is a key event during Bb infection." (PMID 38149246, 2023). "Levels of this gene decreased in both age groups by day 9 post-infection, although less so in aged neutrophils, leading to aged neutrophils expressing significantly higher Cxcl2 than their young counterparts on day 9 post-infection." (PMID 37852965, 2023).
infection (continued). "We quantified Cxcl2 gene expression by neutrophils using a violin plot and accordingly found that levels of this gene were highest on day 3 post-infection with young neutrophils expressing Cxcl2 at significantly higher levels than aged neutrophils." (PMID 37852965, 2023). "Chemokines are proteins (such as IL-8, MCP-1, CXCL2, etc.)with low molecular weight (usually 8-10kD) that attract white blood cells to migrate to the site of infection and play an important role in inflammatory response." (PMID 35581339, 2022). "Neutrophils were found to follow a CXCL1 and/or CXCL2 gradient to sites of infection and stimulation further results in the release of proteases and ROS." (PMID 35529856, 2022). "Proinflammatory cytokines associated with Th17/Th1 response such as IL-6, TNF-α, and IL-1β, and neutrophil-recruiting chemokines including CCL2, CCL3, CXCL1, and CXCL2 were highly produced from day 3 to day 14 after WT infection." (PMID 35696422, 2022). "We have previously shown that CXCL2 production is inhibited in fibrotic mice during infection, and, in the present study, we demonstrate that CXCL2 stimulation increases NE release by naive neutrophils." (PMID 36534439, 2022). "COV patients showed also lower levels of molecules able to recruit neutrophils in the site of infection, such as CXCL2 and CCL5." (PMID 35710943, 2022). "There was a significant increase in mRNA expression of macrophage and neutrophil chemotactic factors CXCL10, CCL3, CXCL1 (KC) and CXCL2 in the lungs of IAV-infected WT mice 3-days post infection." (PMID 35601109, 2022). "Infection led to robust induction of chemokine and interleukin genes, including Il1b, Il6, Ccl2, Ccl3, Ccl4, Ccl7, Cxcl1, Cxcl2, Cxcl5, Cxcl9, and Cxcl10, and related receptor genes, including Ccr1, Ccr4, Ccr5, Ccr5, Ccr7, Cxcr2, Cxcr5, Il1r2, and Il1rn." (PMID 35487885, 2022). "The infection group showed a significant upregulation in IL-1β, IL-6, and CXCL2; the latter is homologous to IL-8 in mice (p < 0.05)." (PMID 35672331, 2022). "By contrast, only moderate effect of the infection was measured on the colonic expression of either Cxcl2, Tnfa or Il6 at day 4 post-infection." (PMID 36266398, 2022). "Expression of macrophage and neutrophil chemoattractants CXCL10, CCL3, CXCL1 and CXCL2 in the lung tissue were significantly lower in NOX4 TG mice compared to the WT mice at 3-days post infection." (PMID 35601109, 2022). "The expression levels of interleukin (IL)-6 and CXCL1/CXCL2 in MZ B cells increased significantly in mice at 3–4 h after infection with S. aureus, then decreased at 24 h post-infection." (PMID 34040603, 2021). "Specifically, neutrophils can employ a positive feedback mechanism driven by high levels of CXCL2 to enhance their recruitment to the sites of infection and antibacterial activity." (PMID 34040603, 2021). "Overexpression of CXCL2, TNFAIP3, ATF3, and CXCL3 increased VEEV-TC-83 infection, suggesting rate limitation associated with these candidate proviral factors." (PMID 33788849, 2021). "Specifically, macrophages have been shown to recruit neutrophils in the early stage of infection via CXCL2 expression." (PMID 33608410, 2021). "MiR-193a-3p and miR-1184, which expressions are decreased upon H37Rv infection, and both putatively target CXCL2, are also involved in apoptosis." (PMID 34276658, 2021). "CXCL1 and its paralog CXCL2 have been shown to mediate neutrophil recruitment and activation to different tissues in response to infection." (PMID 34686752, 2021). "ELISA confirmed that the increased cytokine production (CXCL1, CXCL2, IL-6, and IL-1β) induced by bacterial infection was reverted by AnxA1 treatment in WT mice at 14 h after infection." (PMID 33318141, 2021). "Blocking the action of CXCL1/CXCL2 by injecting anti-CXCL1 and anti-CXCL2 antibodies 1 h before S. aureus infection significantly suppressed the recruitment of neutrophils to the MZ at 3 h post-infection." (PMID 34040603, 2021).
infection (continued). "After infection, TLR4-deficient mice also showed increased mRNA expression of proinflammatory cytokines IL-1α and CXCL2 and type-1–associated cytokines interferon [(IFN)-γ and IL-18] when compared with wild type BALB/c mice." (PMID 34684184, 2021). "Among the strongest H37Rv-specific host genes/miRNAs displaying inverse expression levels, CXCL2 is over-expressed following H37Rv infection, and targeted by 3 miRNAs (miR-1184, miR-26b-3p and miR-130b-5p)." (PMID 34276658, 2021). "In mice that are designated susceptible to P. aeruginosa infection (cornea perforates) such as the C57BL/6 strain, significant upregulation of IL-1β and CXCL2 occurs post-infection (p.i.)." (PMID 34684184, 2021). "A quantitative analysis performed by using MetaMorph software indicated that depletion of CXCL1/CXCL2 before infection prevents neutrophil recruitment to the MZ." (PMID 34040603, 2021). "This is indicated by the expression of Zeb2 and Cxcl2 marker genes, which are exclusive to the AM_2 population in uninfected mice, but become up-regulated by AM_2 and IM_1 bystander cells upon infection." (PMID 34292313, 2021). "Our RT-qPCR results confirmed that the Cxcl1 and Cxcl2 mRNA levels were increased at 4 h post-infection but were decreased at 24 h post-infection." (PMID 34040603, 2021). "At early time points of C. albicans infection, Trim31−/− mice showed significantly reduced secretion of IL-6, TNF-α, IL-12, CXCL1, and CXCL2 in their serum at 24 h post-infection as compared with Trim31+/+ mice." (PMID 34362877, 2021). "We noted a strong upregulation of genes encoding for CXCL2, CXCL3, CXCL10, IFNβ-1, IFNλ-1, -2, -3, endothelin 1 (EDN1) and IFIT-1, -2, -3 following E-30 infection." (PMID 32872518, 2020). "The level of CXCL2 mRNA was significantly higher in the lungs of klotho KO mice than in those of klotho WT mice at 1 day post-infection." (PMID 33329595, 2020). "An interesting finding was that some mediators were more affected by TLR2 loss in the brain compared to the galea, including IL-1β, CCL2, TNF-α, IL-6, and CXCL2, which was particularly evident at day 14 post-infection." (PMID 32290861, 2020). "Here, both basolateral and apical infection led to the upregulation of CXCL2 and CXCL3 in HIBCPP cells." (PMID 32872518, 2020). "We found upregulated genes that were also upregulated following basolateral infection, such as CXCL2, CXCL3, CXCL10, IFNβ-1, IFNλ-1, -2, -3, endothelin 1 (EDN1) and IFIT-1, -2 and -3." (PMID 32872518, 2020). "When compared with SIRT3 WT BMDMs or PMs, SIRT3 KO BMDMs or PMs showed a significantly increased mRNA levels of Tnf, Il6, and Cxcl2 after infection with Mabc-R." (PMID 32835604, 2020). "For this, we measured the expression levels of lung Cxcl1, Cxcl2 and Cxcl5 during infection with low or high doses of Mtb." (PMID 32203062, 2020). "A previous study has shown that basolateral infection of HIBCPP cells with E-30 resulted in an increased expression of CXCL2 and CXCL3, two chemokines that play a role during inflammation processes." (PMID 32872518, 2020). "The chemokine, CXCL2, is produced by a variety of cell types such as macrophages, epithelial cells, hepatocytes, and monocytes in response to infection or injury." (PMID 33374309, 2020). "Levels of IL-1β, IL-6, CCL2, CCL3, CXCL1, and CXCL2 were significantly greater 6 h following infection than in mock-infected mice (P < 0.05) but were similar among wild-type, CCR2−/−, and Nr4a1−/− mice." (PMID 31818962, 2020). "Transcription analyses at 4 h post infection revealed an over 30- and 1,000-fold increment in the transcription of the chemokine genes Ccl2 and Cxcl2, respectively." (PMID 33117382, 2020). "Mabc-R-mediated mRNA generation of Tnf, Il6, and Cxcl2 was significantly increased in BMDMs from SIRT3 KO mice compared to SIRT3 WT mice after infection in a time-dependent manner." (PMID 32835604, 2020).
infection (continued). "The level of CXCL2 mRNA in the lungs of klotho KO mice increased at 1 day post-infection and subsequently decreased at 3 days post-infection." (PMID 33329595, 2020). "These factors are critical for virulence and, during infection, induce secretion of interleukin-6, CXCl1, and CXCL2, assist with bacterial dissemination to the spleen, and stabilize hypoxia inducible factor-1a (HIF-1a)." (PMID 32390954, 2020). "CXCL-2 is rapidly produced at the infection site and recruits phagocytic effector cells into the local infection site where pathogens such as C. albicans are present." (PMID 33396406, 2020). "Chemokine ligand-2 (CXCL2) is a chemotactic chemokine produced by colonic epithelial cells and macrophages in response to infection or injury; IL8 is the most active neutrophil chemoattractant that is upregulated during inflammation." (PMID 32650602, 2020). "The protein levels of IL-5, IL-6, IFNγ, G-CSF, and MCP-1 (CXCL2) were significantly higher in ZBP1−/− mice compared to the WT mice at day 4 after infection." (PMID 31572318, 2019). "Further, the mononuclear phagocytes were shown to upregulate CXCL2 in response to infection, and thereby contributed to the recruitment of neutrophils." (PMID 31921099, 2019). "Ly6C+ macrophages produce the cytokine TNF in response to infection, which activates resident Ly6C− macrophages to secrete CXCL2 and promote migration of neutrophils." (PMID 31551993, 2019). "Compared to uninfected cecal tissues, infection led to the significant upregulation (10- to 500-fold) in transcription of the neutrophil-attracting chemokines Cxcl1 and Cxcl2." (PMID 31848276, 2019). "CXCR1, and mainly CXCR2 expression, on neutrophils grants an additional form of chemotaxis away from the bone marrow via their respective ligands, CXCL1 and CXCL2, which are produced by macrophages and mast cells at the site of infection." (PMID 30791481, 2019). "(d) Serum levels of the cytokines IL-1β, IL-10, CCL20 and CXCL2 2 hr after infection by CC17 GBS (n = 9 mice per group)." (PMID 31710290, 2019). "At 2 h post infection (p.i.), enhanced accumulation of mRNAs for Cxcl1, Cxcl2, Cxcl3, and Cxcl5, as well as Ccl3 and Ccl4, was evident (determined as differentially expressed using a 5% FDR)." (PMID 29636754, 2018). "Our results show a statistically significant increase in the expression of CSF3 and CXCL2 in KO compared to WT mice at 6 h post-infection." (PMID 30333823, 2018). "Conversely, CXCL‐1, CXCL‐2, and G‐CSF were shown to be expressed mainly by AM in the initial phase of infection (around 6 h post‐infection)." (PMID 29119707, 2018). "Conversely, the transcript level of Cxcl2 was significantly downregulated in WT mice at week 5 compared to week 3, indicating a shift from an innate to an adaptive immune response and better infection control." (PMID 30534124, 2018). "Infection with the ΔgliP mutant significantly stimulated the expression of CXCL2, CCL3, CCL4, CCL7, TNF-α, and IL-6, whereas infection with the Δaspf1 ΔgliP double mutant significantly decreased the expression of CXCL2, CCL7, TNF-α, and IL-6." (PMID 30052103, 2018). "We observed a clear signature of up regulated CSF3, as well as CXCL2 6 h post-infection genes in Ghrh−/−." (PMID 30333823, 2018). "In the present study CXCL2 also was induced by the infection, with similar levels of expression between the first and second waves." (PMID 28591228, 2017). "Meanwhile, the mRNA expression of Ifnα, Ifnβ, Ifnγ, Tnfα, and selective chemokines (Cxcl1, Cxcl2, and Ccl5) by leukocytes was lower in the blood of Ddx25-Tg mice on day 1 post-infection." (PMID 28824886, 2017). "CXCL2 (IL-8 human homolog) is known to be central for the recruitment of PMN in the lungs during infection." (PMID 28887540, 2017). "This is followed by the production of neutrophil chemoattractant chemokines including CXCL1 and CXCL2 mainly produced by activated tissue residential macrophages, which in turn induce neutrophil recruitment to the site of infection." (PMID 28817707, 2017).